CCL20 (C-C motif chemokine ligand 20)
Diseases named in the same sentence as CCL20 in open-access papers (continued):
Sharing a sentence is not in itself a finding about the gene and the disease.
tumor (continued). "We noted that T cells with high reactivity toward RCAN1-4 presented significantly greater expression of many tumor-reactive T cell-related genes, most notably CCL20, SDC4, and SPRY1, with greater than twofold greater expression than T cells with low/no response to RCAN1-4." (PMID 41436600, 2026). "Moreover, we observed that among all chemokines analyzed, CCL20 was uniquely and markedly expressed by tumor cells." (PMID 41399390, 2026). "Unlike other chemokines that are primarily secreted by immune cells, CCL20 expression by tumor cells may represent a distinct mechanism of tumor-intrinsic immune evasion, which warrants further investigation." (PMID 41399390, 2026). "In this way, a possible hypothesis might be that the induction of Blastococcus would drive the tumor progression by the increased expression of CCL20 and mDCs." (PMID 40552117, 2025). "Therefore, we focused on the process that tumor-intrinsic SENP3 promotes macrophage infiltration by augmenting CCL20 secretion." (PMID 39755756, 2025). "In the early stages of tumor progression, the presence of cDC1s in the TME is limited due to the preferential recruitment of tumor‐promoting immune cells by chemokines such as C‐X‐C motif chemokine ligand 1 (CXCL1), C‐C motif chemokine ligand 2 (CCL2), and CCL20, which are secreted by tumor cells." (PMID 40667699, 2025). "Indeed, HCC expression of CCL20 is associated with tumor size, tumor number, and vascular invasion, and HCC patients with high CCL20 expression have poorer overall survival in comparison with those with low CCL20." (PMID 40564180, 2025). "Similarly, Fusobacterium nucleatum was shown to have a major impact on aggressive tumor behavior through the activation of chemokines, such as chemokine (C-C motif) ligand 20 (CCL20)." (PMID 41155504, 2025). "Promotes tumor growth and immune suppression via the CCL20 axis." (PMID 39973938, 2025). "This establishes the association between the Hh pathway and the CCL20/CCR6 axis in HCC progression, highlighting a mechanism by which Hh pathway activation may drive tumour‐promoting inflammation in HCC." (PMID 40913253, 2025). "Additionally, GSTP1 ligands produced by MDSCs in state 2 interacted with TRAF2 receptors on malignant cells, while CCL20 secreted by tumour cells bound to CCR6 receptors on T cells and germinal centre B cells." (PMID 40429821, 2025). "Additionally, IHC staining revealed decreased percentages of monocyte/macrophages, which are detected by F4/80, Ly6C or CD115 markers, in tumours with GLI1 KO or CCL20 KO cells compared to WT tumour cells." (PMID 40913253, 2025). "Our study suggested that inhibiting CCL20 or CXCL3 can directly inhibit tumor progression." (PMID 40179015, 2025). "However, the molecular and regulatory mechanisms of CCL20 in the tumor microenvironment are complex, and more rigorous research is needed." (PMID 39985603, 2025). "Moreover, IL-17 induces further CCL20 production by tumour cells, establishing a detrimental feedback loop that exacerbates immune evasion and tumour progression." (PMID 40429821, 2025). "Additionally, the tumor weight, infiltration level, and anti‐tumor activity of CD8+ T cells in the shNC tumors treated with anti‐CCL20 antibody were comparable to those in the shGal1 tumors treated with anti‐CCL20 antibody." (PMID 39853961, 2025). "In the tumor microenvironment, CCL20 enhances the recruitment of immunosuppressive cells including regulatory T cells (Tregs), tumor-associated macrophages (TAMs), tumor-associated neutrophils (TANs), and myeloid-derived suppressor cells (MDSCs) to enhance tumor progression." (PMID 39985603, 2025). "CCL20 is known to stimulate the migration and proliferation of tumor cells." (PMID 41019045, 2025). "Mechanistically, we hypothesize that this relationship is mediated by the chemokine CCL20, which is secreted by tumor cells and facilitates the recruitment and polarization of macrophages toward an M2 phenotype." (PMID 41312091, 2025).
tumor (continued). "Similarly, circSMARCC1-mediated CCL20 expression facilitated macrophage recruitment, thus promoting tumor progression." (PMID 39985603, 2025). "Furthermore, CCL20 is more highly expressed in KICH than in both KIRC and KIRP, supporting earlier research that mutations in the EGFR/Ras pathway promote tumor growth by increasing EGFR/Ras expression, which boosts the immune-activating chemokine CCL20." (PMID 40649942, 2025). "Additionally, CCL20 can drive Tregs infiltration to impair antigen presentation of HLA-DR on type 2 conventional dendritic cells, enhancing tumor progression." (PMID 39985603, 2025). "The HPV E6/E7 genes suppress CCL20/MIP3α secretion, impairing Langerhans cell migration, while HPV-positive cells secrete elevated levels of G-CSF, IL-6, IL-8, promoting the recruitment of tumor-associated neutrophils and M2 macrophages." (PMID 40264780, 2025). "In the same study, CCL20 upregulated by HOXD3 promoted tumor metastasis and angiogenesis." (PMID 39985603, 2025). "Furthermore, inflammatory macrophages, such as SPP1+ and CCL20+ macrophages, exhibited increased cell-cell communication with tumor cells in the high GLMscore group, potentially mediated by the PPIA-BSG signaling pathway." (PMID 40443528, 2025). "In response to tissue damage and inflammation in TME, CAFs attract polymorphonuclear leukocytes by secreting CXCL12, which in the presence of tumor-derived CCL20, additionally upregulate PD-L1 expression in neutrophils consequently inhibiting antitumor activity of T cells." (PMID 40940764, 2025). "For example, the chemokine CXCL10 promotes the infiltration of T cells into the tumor microenvironment, enhancing anti-tumor immunity, while CCL20 recruits Tregs via the FOXO1/CEBPB/NF-κB signaling pathway, thereby promoting chemotherapy resistance in colorectal cancer." (PMID 41200171, 2025). "Additionally, we encapsulated the Toll-like receptor 7/8 agonist R848 within the CCR6-modified macrophage membrane (CCR6-MM) to polarize M2-type TAMs to the M1 phenotype, reducing CCL20 secretion and transforming the immunosuppressive tumor microenvironment." (PMID 41625363, 2025). "Although CCL20 mRNA expression was lower in tumor tissues than in normal control tissues, the CCL20 serum concentration was higher in patients than in matched healthy donors, confirming that serum chemokines originate from various cells across different tissues and organs." (PMID 40925909, 2025). "We therefore hypothesized that chaperonins might be related to the secretion of CCL20 by tumor cells." (PMID 41312091, 2025). "Additionally, in vivo, tumour migration and matrigel plug assays in nude mice revealed that CCL20 played a role in regulating tumour migration and angiogenesis." (PMID 38493218, 2024). "In addition, positive correlations between pretreatment serum CCL20 concentration and overall tumor stage and between posttreatment serum CCL20 concentration and indicators such as recurrence and metastasis rates were found in a prospective cohort." (PMID 39483474, 2024). "In patients positive for F. nucleatum, a higher cancer-specific mortality rate was observed with the bacterium linked to the activation of chemokines, particularly C-C motif chemokine ligand 20 (CCL20), which is involved in immune cell migration and tumor progression." (PMID 39676876, 2024). "In addition, it also exerted a synergistic interaction with CCL20 to enhance the recruitment of type‐1 conventional DCs, strengthened anti‐tumor immune responses, and promoted tumor regression." (PMID 38864372, 2024). "This is further supported by the increase in the circulating levels of CCL20 observed in this cohort of patients, in our previous study, and by a number of studies that have detected infiltration of Treg cells in the tumor microenvironment of HCC and CCA patients." (PMID 39408071, 2024). "Rescue assays showed that knockdown of CCL20 could impair the tumour‐promoting effects of THIL in CRC cells." (PMID 38809918, 2024).
tumor (continued). "Furthermore, increased levels of IL-8 and CCL20 have been reported in the tumor tissue of HCC patients, correlating with poor prognosis and decreased overall patient survival." (PMID 39215104, 2024). "CCR6, the sole receptor of CCL20, plays a regulatory role in CCL20-induced tumour migration." (PMID 38493218, 2024). "Additionally, upon more extensive analysis, a significant correlation was identified between VDR expression and CCL20 expression, with CCL20-positive cells also being surrounded by higher M2/M1 ratios in the 200 μm of tumor and stroma." (PMID 38600588, 2024). "Importantly, Tc17 cells infiltrating the tumor have been demonstrated to possess protumoral activity, and to express high levels of CCL20, thereby recruiting Tregs." (PMID 39408071, 2024). "Moreover, it has been reported that CCL20 can stimulate the proliferation, invasion, angiogenesis and therapy resistance of cancer cells, thereby facilitating tumor growth." (PMID 38730689, 2024). "Th17 cells are a veritable cytokine factory, producing a range of cytokines and chemokines, including IL-17A, IL-17F, IL-21, IL-22, TNF-α, and CCL20, which modulate the behavior of fibroblasts, endothelial cells, epithelial cells, macrophages, and tumor cells, thereby sculpting the TME." (PMID 39906741, 2024). "Additionally, when CCL20 was administered in vivo, it exhibited a tumor inhibitory effect compared to the IgG group." (PMID 38600588, 2024). "However, there are exceptions, as demonstrated in non-small cell lung cancer, in which CCL20 promotes tumor progression by recruiting Th17 cells." (PMID 37680632, 2023). "It has been shown that the tumor-derived cytokine CCL20 upregulates IDO expression, and IDO also inhibits CD8+ T cell responses and induces tumor immune evasion, so it is highly likely that the strong rise of CCL20 in PBK overexpression inhibits CD8+ T cells via IDO1." (PMID 37993518, 2023). "Furthermore, intra-tumoral Tc17 cells also express CCL20, CCR4, CCR6, and CXCR6 which have previously been associated with tumor progression in HCC patients." (PMID 38567057, 2023). "Suggested mechanisms for a contribution of Tc17 cells to an immunosuppressive tumor microenvironment include the recruitment of regulatory T cells (TREG) via the CCR6-CCL20 axis indicated by increased levels of CCL20 in HCC samples, especially in those infiltrated with IFN-γ-negative Tc17 cells." (PMID 38567057, 2023). "We observed that CCL20 overexpression remarkably promoted tumor growth." (PMID 36859354, 2023). "Furthermore, Ccl20 levels continuously increased as the PpardTG mice aged from 10 to 55 weeks while the tumor progressed, suggesting the potential value of Clc20 as a GAC progression marker." (PMID 37572185, 2023). "Furthermore, we identified several tumour-associated macrophages, including C1QC+ macrophages, ISG-15+ macrophages, NLRP3+ macrophages and CCL20+ macrophages." (PMID 37735150, 2023). "In addition, the role of CCL20 in the TIME is manifested mainly through the recruitment of Th17 cells, immature DCs, Tregs and tumor-associated macrophages (TAMs)." (PMID 37545521, 2023). "We not only uncovered connection between expression of CCL20 and worse stage in clinical settings, but also uncovered disrupted CD8+ T cells function with exhaustion phenotype and M2 infiltration triggered by ccl20 overexpression in U14 cancer cell lines in immune-competent murine tumor model." (PMID 37183243, 2023). "Finally, we constructed lentivirus inducted stable overexpression of CCL20 in U14 (OE-CCL20), and verified the successful overexpression by qRT-PCR, western blot, flow cytometry and IHC.Then subcutaneous U14 tumor models were established in C57BL/6 mouse." (PMID 37183243, 2023). "Furthermore, CCL20 knockdown combined with SLC7A2 overexpression availably weakened the tumor growth in vivo." (PMID 36969014, 2023).
tumor (continued). "Furthermore, we report that high CCL20 and CXCL8 serum levels were associated with microvascular invasion, a characteristic of advanced tumor stages." (PMID 36982370, 2023). "Moreover, the median CCL20 gene expression in normal tissue was 917 (Q1: 487, Q3: 1898) compared to 3339.5 (Q1: 1448, Q3: 7536) in tumour tissue and 1460 (Q1: 691, Q3: 3620.5) in metastatic tissue (p = 2.4 × 10−58, Kruskal–Wallis test)." (PMID 36835258, 2023). "In addition, another research demonstrated that tumor-specific myeloid cells in bone metastasis microenvironment can produce local chemokine CCL20 to increase the exhaustion of T cell population." (PMID 37880708, 2023). "Furthermore, the tumor-promoting effects of CCR6/CCL20 within the tumor microenvironment have been reported in many cancer types, such as renal cell carcinoma, gastric cancer, cervical cancer, and lung cancer." (PMID 37218898, 2023). "Further through CIBERSORT analysis, FISH and IHC analysis of clinical specimens and flow cytometry analysis of subcutaneous mouse tumor model, CCL20 was identified as inducer of desert-like TME with more M2 macrophages infiltration and as indicator of worse clinical stages." (PMID 37183243, 2023). "Similarly, F. nucleatum in CRC promoted CCL20 expression in tumor cells, which further induced M2 macrophage polarization and enhanced the metastasis of cancer cells." (PMID 37771912, 2023). "This hypothesis was also supported by the observation that Th17 cells could stimulate the expression of the chemokine CCL20 in tumor tissue and promote the migration of DC by CCL20-CCR6 dependence." (PMID 35459193, 2022). "In addition, numerous studies have found that the characteristic chemokines of Type 17 T cells, such as IL-17A, IL-17F, GM-CSF, and CCL20, recruit T cells, B cells, neutral granulocytes, and macrophages into tumor tissue in various tumor models." (PMID 35459193, 2022). "Collectively, the CCL20 expression level in tumor tissues had a predictive prognosis for LUAD." (PMID 35864953, 2022). "The expression levels of both CCL20 gene and the signatures of M_C3_CCL20 were higher in tumor." (PMID 35102420, 2022). "Our results showed that CCL20 levels could distinguish OC from benign diseases, including endometriotic cysts." (PMID 36387204, 2022). "We further performed subcutaneous tumorigenesis experiments, exploring whether CCL20 keeps the tumor-promoting effects within complicated intracorporeal environments." (PMID 35864953, 2022). "In addition, it seems that the effect of CCL20 on other tumorigenic cells is significant and that CCL20 ultimately supports tumor progression." (PMID 35408440, 2022). "The telomerase reverse transcriptase (TERT)-positive tumor treated with CCL20/IL15-armed oAd that replicated under control of the TERT promoter plus NK showed significantly higher antitumor efficacy than either of the treatments alone and induced tumor-specific cytotoxicity of CTLs." (PMID 36091031, 2022). "Moreover, the expressions of CXCL14, CCL20, CCL24, and CCL26 were associated with tumor purity and infiltration of CD4+ T cell, CD8+ T cell, B cell, macrophage, dendritic cell, and neutrophil in PCa." (PMID 36275733, 2022). "Researchers have found that docetaxel could rescue immunity functions against tumor cells by reducing their secretion of CCL20 interacted with CCR6+ Tregs." (PMID 35497874, 2022). "A recent study also reported that RORγ agonists increased the expression of CCR6 and CCL20 in Tc17 cells, and this might contribute to the better migration of Tc17 cells into the tumor and recruitment of Tc1 cells." (PMID 35459193, 2022). "The CCL20 chemokine is also crucial in oncological gynecology in neoplasms such as ovarian and EC." (PMID 35408440, 2022). "In HCC tissue, CCL20 expression is closely related to tumor size and vascular invasion." (PMID 35308139, 2022).
tumor (continued). "Thus, by enhancing the function of Type 17 T cells, 8–074 treatment increased the secretion of CCL20 in the tumor, promoting tumor infiltration of both CD8+ T and MoDC and making the anti-tumor immune response of Type 17 T cells efficient and persistent." (PMID 35459193, 2022). "Furthermore, the product of CCL20 (downregulated 10-fold in hPARG-expressing cells) recruits Th22 cells to the tumor microenvironment and promotes cancer stemness." (PMID 35585513, 2022). "In vivo experiment showed that tumor growth was remarkably repressed after CCL20 knockdown." (PMID 35864953, 2022). "Selective recruitment of regulatory T cells (Tregs) by CCR6 and its ligand CCL20 in the tumor microenvironment may inhibit the proliferation of CD4CD25 and INF-γ secretion and promote the development of HCC." (PMID 36231045, 2022). "Hence, we analyzed the relationships between the signature and TIP-related genes, and the results showed that cold tumor genes such as CXCL2 and CCL20 and hot tumor genes such as CXCR3, CXCL11, and PDCD1 were upregulated in the high-risk group in both cohorts." (PMID 35938001, 2022). "In addition, CCL20 can indirectly promote cancer progression through immune cell control to reshape tumor microenvironment." (PMID 35480896, 2022). "CCL20 produced in the tumor microenvironment may also selectively attract Th17 cells expressing high levels of CCR6." (PMID 36107259, 2022). "On the contrary, CCL20 deficiency counteracted the increased population of CCR6+ CD8+ T cells and attenuated the anticancer effect of the combined treatment of ICB and EPS-R1 in tumor-bearing mice." (PMID 36726985, 2022). "Taken together, CCL20 secreted from P2Y11-activated M2 macrophages may directly promote tumor growth or indirectly support tumor progression through the recruitment of regulatory and pro-angiogenic immune cells." (PMID 36107259, 2022). "Very recently, EN2 was reported to play an oncogenic role in tumor progression via CCL20 in CRC43." (PMID 35169223, 2022). "From animal studies, other proposed anti-tumor mechanisms of probiotics have included greater regulation of Tregs or TGF-β and increased recruitment of Th17 via the CCL20/chemokine receptor 6 axes in metastatic disease, both mechanisms of which involve alterations to the tumor microenvironment." (PMID 35474500, 2022). "The result showed that CCL20 knockdown significantly repressed tumor growth in the xenograft model." (PMID 35864953, 2022). "We further investigated whether CCL20 expression in tumor tissues has effects on clinical outcomes of LUAD patients." (PMID 35864953, 2022). "However, CCL20 appears to engage in a complex interaction with other factors in the tumor microenvironment." (PMID 34569432, 2021). "Notably, there is the need to highlight and understand the key factors regulating the tumor-promoting effects of CCL20 in tumor progression." (PMID 34569432, 2021). "High CCL20 expression increases the migration of Tregs cells towards the tumor." (PMID 34837898, 2021). "However, further comprehensive analysis using more tumor cell lines should be conducted to elucidate the actual role of CCL20 in TSCC." (PMID 34178651, 2021). "Furthermore, Th17 cells have been shown to induce the production of CCL20 in tumor tissues, which recruits CCR6-expressing immature DCs to tumor tissues in a murine melanoma model." (PMID 34885241, 2021). "In this report, we describe a signaling pathway from PERK through C/EBPδ in cancer cells, which contributes to expression and secretion of CXCL8/IL-8 and CCL20, two chemokines that have well-documented tumor promoting effects through direct action on cancer cells as well as various immune cells." (PMID 34725321, 2021). "A significant positive correlation was found between CCL20 and CD66b+ neutrophils in tumor tissues." (PMID 34519637, 2021).